FASLG (Fas ligand)
Diseases named in the same sentence as FASLG in open-access papers (continued):
Sharing a sentence is not in itself a finding about the gene and the disease.
cancer (continued). "Direct oncolysis by viral replication is facilitated using various signaling pathways involving TNFα, Fas ligand (FasL), TNF-related apoptosis-inducing ligand (TRAIL), ROS and others, and can lead to different types of cell death in different cancers." (PMID 33920168, 2021). "NK cells release TNF-related apoptosis-inducing ligand (TRAIL), TNF, Fas ligand (FASL), and death receptor 3 (DR3) ligand to induce cancer cell death." (PMID 34682815, 2021). "Murine and human iNKT cells display on their surface the cytotoxicity‐related molecules Fas ligand and TRAIL, used for their cancer‐killing function in vitro and in vivo." (PMID 34535957, 2021). "These four pathways were proteoglycans in cancer (ANK2, FASLG, HSPG2, PTPN11, STAT3, and VEGFA), HIF-1 signaling (ARNT, STAT3, and VEGFA), FoxO signaling (FASLG, SMAD4, and STAT3), and ECM-receptor interaction (HSPG2 and LAMA2)." (PMID 29300322, 2018). "Transmembrane CD95L (Fas ligand) can be cleaved to release a promigratory soluble ligand, cl-CD95L, which can contribute to chronic inflammation and cancer cell dissemination." (PMID 27302366, 2016). "Although many anticancer drugs kill cancer cells through apoptosis, our pervious study indicated procaspase-3 did not play an indispensable in etoposide, MG132, staurosporine and Fas Ligand- induced apoptosis." (PMID 25754465, 2015). "Death receptor ligands, such as Fas-ligand and tumor necrosis factor-related apoptosis inducing ligand (TRAIL) are potentially useful for combination therapy of cancer." (PMID 22389673, 2012). "Approaches that target the extrinsic apoptotic pathway to induce cancer death include the use of DR agonists such as Fas ligand, tumor necrosis factor-alpha (TNFα), TNF-related apoptosis-inducing ligand (TRAIL), Apo2L/TRAIL, and CD95L/FasL 26,36." (PMID 38169587, 2024). "The role of the Fas ligand, or CD95L, has been widely acknowledged as a receptor–ligand system that triggers apoptosis, ensuring immune homeostasis and playing a vital part in eliminating cancer cells." (PMID 39796695, 2024). "Our findings revealed a positive correlation between the expression levels of LAG3 and IFNG (R = 0.76, p < 0.001), PRF1 (R = 0.75, p < 0.001), FASLG (R = 0.75, p < 0.001), GZMH (R = 0.74, p < 0.001), NKG7 (R = 0.74, p < 0.001), and PDCD1 (R = 0.73, P < 0 0.001) in pan-cancer tissues." (PMID 38115039, 2023). "We have earlier reported that under the influence of cancer conditioned media mimicking the cancer microenvironment, CVMSCs express a variety of anti-proliferative proteins such as IL-27, MSTN, and TGF-β2, and pro-apoptotic proteins including IFN-α2 and FASLG." (PMID 37298519, 2023). "Out of the total number of monitored genes (n = 84) in the Human Cancer PathwayFinderTM PCR Array, we were able to detect all of them, and only in the control group was there not a gene for the Fas ligand in any of the samples." (PMID 36142793, 2022). "Against all tested cancer cell lines, the BAFF CAR-T cells released significantly higher levels of the pro-inflammatory cytokines TNF-α and IFN-γ, lytic enzymes granzymes A and B and perforin, soluble Fas ligand (sFasL), and granulysin." (PMID 35017485, 2022).
cancer (continued). "Furthermore, cytotoxic T cells express FASLG (Fas ligand, CD178), thereby inducing cancer cell apoptosis through its binding with FAS (Fas cell surface death receptor, CD95)." (PMID 35392092, 2022). "Moreover, NK cells express tumor necrosis factor–related, apoptosis-inducing ligand family TRAIL, and FAS ligand (FASL), which interact with TRAIL receptors and FAS ligands in cancer cells, respectively." (PMID 36199754, 2022). "In this work, we identified five proteins, namely, Gal-1, Gal-9, MMP7, FASLG, and COL9A1, that based on their known function in endometrial and other cancers might represent useful early-stage EC biomarkers, upon a validation phase." (PMID 36009404, 2022). "In the case of cancer, the CD8+ T cells recognise surface-expressed cancer antigens on tumours and initiate apoptosis through cell-mediated cytotoxicity by releasing apoptotic factors such as Perforin, Fas Ligand and Granzymes." (PMID 34276688, 2021). "CD4+ TILs can recruit dendritic cells that can prime T cells to exert their cytotoxic effects by secreting perforin, granzyme B, or Fas ligand (cell death receptor ligand; FasL; CD95L), which may directly kill cancer cells." (PMID 30200478, 2018). "Fas ligand (FasL) and tumor necrosis factor-related apoptosis-inducing ligand (TRAIL) provide a death signal via the extrinsic apoptotic pathway, activating caspase-8 in cancer cells." (PMID 29876007, 2018). "We found primary human NK cell, unlike NK cell line, killed adherent cancer target mainly by lytic granule-independent mechanism, in particular through Fas ligand (FasL)." (PMID 27323411, 2016). "Fas ligand (FasL) and tumor necrosis factor (TNF)-related apoptosis-inducing ligand (TRAIL) can provide a death signal via the ‘extrinsic’ apoptotic pathway, activating caspase-8 in cancer cells." (PMID 25333266, 2014). "Moreover, NK cell-induced death in cancer cells may be stimulated through death receptor-mediated apoptosis including TNF-related apoptosis-inducing ligand, Tumor Necrosis Factor (TNF), and Fas ligand." (PMID 40342534, 2025). "This reduction in endocytosis has been observed to retain Fas receptors across multiple cancer cell lines without altering normal cells, enhancing sensitivity to the soluble Fas ligand and inducing cell death in two-dimensional culture, organoids, and in vivo models." (PMID 39092762, 2024). "Meanwhile, homozygous CNV analysis showed that FADD in 22 cancer types, FASLG in 25 cancer types, RIPK1 in 22 cancer types, TLR3 in 15 cancer types, TNF in 23 cancer types, FAS in 15 cancer types, MLKL in 12 cancer types, and RIPK3 in 17 cancer types had homozygous amplifications." (PMID 35748782, 2022). "In fact, quercetin suppresses cancer cell growth and promotes phase G2 cell cycle arrest and apoptosis in EGFR-overexpressing HSC-3 and TW206 cells, thus inducing the activation of FOXO1, the knockdown of which attenuates the quercetin induction of p21 and Fas ligand (FasL) expression." (PMID 32486484, 2020). "Tumor necrosis factor (TNF), TNF-related apoptosis inducing ligand (TRAIL), Fas-ligand (Fas-L), TNF-related factor-1 and 2 (Traf1/2) etc. are some of the key molecules that belong to the extrinsic pathway or death receptor signaling that are known to be de-regulated in cancers." (PMID 22974127, 2012). "Since TRAIL induces apoptosis in transformed or tumor cells but not in normal cells, it is considered to be a promising cancer therapeutic agent, better than other TNF superfamily members, such as TNF and Fas ligand, which have no selectivity for normal and cancer cells." (PMID 22179661, 2012).
cancer (continued). "Furthermore, in a Cancer Pathway Finder RT2 PCR array study (SA Biosciences) (data not shown) significant increases in the expression of the CASP9 and FASLG genes in response to S. frutescens extract indicate that the extract may induce apoptosis via the intrinsic as well as extrinsic pathways." (PMID 27656236, 2016). "Early attempts to treat cancer using the TNF and Fas ligand (FasL) as DR agonists showed disappointing results due to lack of efficacy or prohibitive preclinical toxicity." (PMID 36496977, 2022). "The antigen-negative cancer cells can be targeted via FAS and Fas Ligand axis, independent of presenting death receptors by the cancer cell." (PMID 36499331, 2022). "Unlike Fas ligand and TNF, TRAIL appears to have limited toxicity for mice and monkeys, suggesting its potential value for cancer therapy." (PMID 15138489, 2004).
infection (187 papers, 2004 to 2025). The state of being infected such as from the introduction of a foreign agent such as serum, vaccine, antigenic substance or organism. "In a previous study, in vivo experimental infection with B. ostreae was associated with a modulation of apoptotic genes including Fas ligand and IAP8." (PMID 30131502, 2018). "CD8+ T cells are known to exert cytotoxic functions, which eliminate the infection via the Fas/Fas ligand (FasL) pathway, leading to the large-scale cell apoptosis and tissue damage, including acini injury." (PMID 39469708, 2024). "Post-vaccination IL-8 and Fas ligand levels were negatively correlated with each other in the naïve group and during initial infection of recovered patients but showed a positive correlation in recovered individuals." (PMID 36366324, 2022). "In this study, CXCL10, IL-2, IL-10, IL-22, MMP-9, and Fas-ligand were identified as discriminatory biomarkers for type I and type II infections." (PMID 34263738, 2021). "We show that treatment with anti-Fas ligand (FasL) prevents lymphocyte apoptosis, upregulates type-1 responses to parasite antigens, and reduces infection in macrophages cocultured with activated CD8 T cells." (PMID 27195678, 2016). "Using the murine infection model for T. cruzi, splenic CD4+ and CD8+ T-cells were shown to express CD95 (Fas/Fas ligand apoptotic pathway) 2–3 weeks post infection." (PMID 27303406, 2016). "Eighteen cytokines were elevated >2-fold relative to controls at 12 weeks of infection, including CD 30L, Fas ligand, Fractalkine, GCSF, IFN-γ, IL1-β, IL4, IL10, IL12p40/p70, IL12p70, IL17, I-TAC, Lymphotactin, MCP-1, MCSF, MIG, MIP-1α, and TIMP-2." (PMID 26079509, 2015). "In addition, WNV infection of mice deficient in perforin, Fas ligand, and TNF-related apoptosis-inducing ligand (TRAIL) resulted in an increased viral burden in the CNS and mortality following infection." (PMID 40632810, 2025). "Finally, exo-GXM accumulates in macrophages during infection, and these cells show increased expression of the apoptotic Fas ligand (FasL)." (PMID 39470312, 2024). "It is important to inhibit apoptosis from the extrinsic pathway since many in vivo stimuli are present during infection such as TNF-α and Fas ligand." (PMID 20429941, 2010). "In this context, Qa‐1‐dependent peptide presentation restrains excessive T‐cell activation, negatively controlling the expression of IFNγ, Fas ligand (FasL) and CTLA‐4 (Cytotoxic T‐lymphocyte antigen 4), and the apoptosis of T cells, which impairs the ability to resist infection." (PMID 41147236, 2025). "Regarding Epstein–Barr virus (EBV)-infection, NKG2D receptor triggering and the cytotoxic pathways of TRAIL and Fas/Fas ligand (FasL) were outlined as the major mechanisms involved in clearing EBV-transformed autologous lymphoblastoid B cell lines by Vγ9Vδ2 T lymphocytes." (PMID 33183352, 2020). "Furthermore, these cells upregulate Fas and Fas ligand (FasL) upon antigenic stimulation, promoting target cell apoptosis and contributing to activation-induced cell death (AICD), thereby maintaining immune homeostasis during infection." (PMID 40825006, 2025). "Our previous study showed that enhanced hepatic NK cell death by NKG2D/NKG2D ligand and Fas/Fas ligand contributed to hepatocyte necrosis in an MHV-3-FHF mouse model, and depletion of NK cells at 24 h post MHV-3 infection via anti-ASGM-1 could improve survival in an MHV-3-FHF model." (PMID 38017505, 2023). "Finally, we are not aware of reports that have measured Fas-ligand and IL-22 on serum or plasma linking their levels to type of infection, and therefore this study is the first, to our knowledge, to report their potential relevancy." (PMID 34263738, 2021). "Comparisons of serum levels of insulin-like growth factor I, II, and binding protein 3, transforming growth factor β-1, soluble fas ligand and superoxide dismutase activity in the subjects with H. pylori infection and those without infection (within case participants)." (PMID 16127223, 2005).
infection (continued). "Comparisons of serum levels of insulin-like growth factor I, II, and binding protein 3, transforming growth factor β-1, soluble fas ligand and superoxide dismutase activity in the subjects with H. pylori infection and those without infection (within control participants)." (PMID 16127223, 2005). "ACE2 as well as Fas‐L (Fas‐Ligand) and TMPRSS4 (transmembrane serine protease 4), two additional genes involved in the infection process of SARS‐CoV‐2 were not expressed neither in AD‐MSCs, WJ‐MSCs nor in BM‐MSCs." (PMID 34821008, 2022).
immune disorders (14 papers, 2015 to 2025). "Among the four genes that were consistently upregulated in ARHL patients (FASLG, NCAM1, MARCO, and NECTIN1), FASLG was prioritized for further validation based on its strong association with immune-mediated apoptosis and its previously reported role in age-related immune dysfunction." (PMID 40971385, 2025).
neurological disorders (11 papers, 2013 to 2024). "Lastly, the increase in Fas ligand in preterm CSF may indicate direct targeting of oligodendrocytes, as it has been associated with induction of oligodendrocyte death in a variety of neurological disorders." (PMID 30258368, 2018).
bacterial infections (6 papers, 2015 to 2023). "Fas ligand (FASL/CD95L) has been shown to induce neutrophil apoptosis, which is accelerated by the processing of the BH3-only protein BH3 interacting domain death agonist (BID) to trigger mitochondrial apoptotic events, and been attributed a regulatory role during viral and bacterial infections." (PMID 29495595, 2018).
cardiac disease (2 papers, 2013 to 2018). "In cardiac disease, functional assessment of miR-21 implicates PDCD4, SPRY1 or SPRY2, Phosphatase and tensin homolog, and Fas ligand as the major targets of miR-21." (PMID 23441172, 2013).
FASLG also shares sentences with these, for which no sentence is quoted: antiphospholipid syndrome (113 papers); Thrombocytopenia (38); Arterial thrombosis (29); rheumatoid arthritis (25); thrombophilia (20); endothelial dysfunction (16); influenza (16); cardiovascular disease (11); Cerebral ischemia (10); nephritis (10); parasitemia (10); Infertility (9); Miscarriage (9); multiple myeloma (9); brain tumor (8); Cirrhosis (8); infectious disease (8); Sjögren’s syndrome (8); acute myeloid leukemia (7); Hyperglycemia (7); lymphoproliferative disorders (7); malignant glioma (7); nasopharyngeal carcinoma (7); neurodegenerative disease (7); thromboses (7); toxic epidermal necrolysis (7); fibrosis (6); graft versus host disease (6); HELLP syndrome (6); idiopathic pulmonary fibrosis (6).
A further 347 diseases each share a sentence with FASLG in 6 papers or fewer.